XRCC2 (X-ray repair cross complementing 2)
Diseases named in the same sentence as XRCC2 in open-access papers (continued):
Sharing a sentence is not in itself a finding about the gene and the disease.
prostate carcinoma (5 papers, 2015 to 2026). A carcinoma that arises from epithelial cells of the prostate gland. "Pathogenic mutations in cancer-driven genes like ATM, CHEK2, PALB2, and XRCC2 have been reported to increase the risk of different malignancies, especially breast and prostate cancers." (PMID 38784039, 2024). "A number of DNA damage response genes have previously been reported to be controlled by AR expression in prostate cancer models, including XRCC2, XRCC3, and PRKDC." (PMID 32117061, 2020). "The association between the presence of polymorphisms rs1801320 and rs1801321 of RAD51, rs10483813 and rs3784099 of RAD51B, rs3218536 of XRCC2, and rs861539 of XRCC3 and the risk of prostate cancer was examined." (PMID 26339569, 2015). "The aim of the present study was to evaluate the relationship between prostate cancer risk and the presence of single nucleotide polymorphisms (SNPs) in the genes involved in HRR, that is, RAD51 (rs1801320 and rs1801321), RAD51B (rs10483813 and rs3784099), XRCC2 (rs3218536), and XRCC3 (rs861539)." (PMID 26339569, 2015). "This analysis identified CASP3, XRCC2, and RIT1 transcripts in circulating EVs as promising biomarkers for the early detection of significant prostate cancer." (PMID 41885368, 2026). "However, considering that the occurrence of cancer is the result of complex interactions between genetic changes and environmental factors, polymorphic variants of the RAD51B, XRCC2, and XRCC3 genes other than those studied may yet have an impact on the development of prostate cancer." (PMID 26339569, 2015).
thyroid cancer (5 papers, 2014 to 2025). "Several different studies have been conducted to examine the association between XRCC2 polymorphism and thyroid cancer in Iranian, Portuguese (Caucasian), Spanish (Caucasian), and Chinese populations." (PMID 38892180, 2024). "Only the combined variants of the RAD52, XRCC2, and XRCC3 genes showed an increased risk of thyroid cancer, as we wrote about in Section 3.2." (PMID 38892180, 2024). "We conducted a comprehensive meta-analysis to explore the association of polymorphisms at XRCC1, XRCC2 and XRCC3 genes with susceptibility to thyroid cancer (TC)." (PMID 34319046, 2021).
glioblastoma (4 papers, 2013 to 2023). The most malignant astrocytic tumor (WHO grade IV). "Overexpression of X-ray repair cross-complementing group 2(XRCC2) is a hallmark of neoplastic cells and especially in glioblastoma tumor cells leads to resistance against anticancer drugs Temozolomide (TMZ)." (PMID 23826488, 2013). "We replicated most of these associations in glioblastoma (Klughammer cohort) where 14 of 17 genes were also positively associated with TERT expression, including four genes related to DNA repair (XRCC2, MSH5, TRAIP, BRIP1)." (PMID 37418389, 2023). "We found that the expression level of XRCC2 was significantly increased in various cancers, including colon adenocarcinoma, rectum adenocarcinoma, and glioblastoma multiforme (GBM)." (PMID 34051735, 2021).
sarcoma (4 papers, 2022 to 2025). A usually aggressive malignant neoplasm of the soft tissue or bone. "BRCA1, RAD51D, and additionally XRCC2 were downregulated in the M6 high-grade sarcoma, whereas XRCC3 was highly overexpressed." (PMID 35978432, 2022). "Both XRCC2 and MAD2L2 higher expression was associated with worse survival in the TCGA sarcoma cohort." (PMID 36110934, 2022).
Azoospermia (3 papers, 2022 to 2024). Absence of any measurable level of sperm,whereby spermatozoa cannot be observed even after centrifugation of the semen pellet. "A homozygote mutation in XRCC2, a paralog of RAD51, was identified within a consanguineous pedigree in which males presented with azoospermia and infertility." (PMID 34402903, 2022).
bladder cancer (3 papers, 2016 to 2024). "Here we aimed to assess the associations of nineteen polymorphisms from seven DNA repair–associated genes (PRAP1, OGG1, APEX1, MUTYH, XRCC1, XRCC2 and XRCC3) with bladder cancer and their interactions in the disease in a Han Chinese population." (PMID 27153553, 2016).
gastric cancer (3 papers, 2015 to 2024). A primary or metastatic malignant neoplasm involving the stomach. "Using machine learning, we screened RAD51D and XRCC2 in the homologous recombination pathway as diagnostic biomarkers for gastric cancer." (PMID 39206620, 2024). "The gastric cancer diagnostic biomarkers RAD51D and XRCC2 that we screened can, to a certain extent, reflect the expression status of genes through radiomic characteristics, which is of certain significance in guiding the selection of chemotherapy regimens for gastric cancer patients." (PMID 39206620, 2024). "The results revealed that there was a significant positive correlation between the expression of RAD51D and XRCC2 and the pathological T stage of gastric cancer." (PMID 39206620, 2024). "To this end, we intersected the gastric cancer diagnostic biomarkers screened by each machine learning method and obtained RAD51D and XRCC2." (PMID 39206620, 2024). "The mRNA levels of RAD51D and XRCC2 in gastric cancer tissues were significantly greater than those in adjacent tissues (p < 0.001)." (PMID 39206620, 2024). "RAD51D expression was not significantly correlated with vascular thrombus or nerve invasion, while XRCC2 expression was greater in gastric cancer patients with vascular thrombus or nerve invasion (p < 0.05)." (PMID 39206620, 2024). "In comparison, the XRCC2 radiomics score was greater in gastric cancer patients with vascular tumor thrombus or nerve invasion (p < 0.05)." (PMID 39206620, 2024). "In the previous results, qRT‐PCR assays measured the expression of RAD51D with XRCC2 in 39 gastric cancer patients." (PMID 39206620, 2024). "In addition, we used the TCGA database to verify that after pairing RAD51D and XRCC2, the mRNA level in gastric cancer tissue was still significantly greater than that in adjacent tissue (p < 0.001)." (PMID 39206620, 2024). "Moreover, our study showed that the expression of RAD51D and XRCC2 was significantly and positively correlated with the clinicopathological features of gastric cancer patients." (PMID 39206620, 2024). "We screened RAD51D and XRCC2 in the homologous recombination pathway as biomarkers for gastric cancer diagnosis by machine learning, and the expression of RAD51D and XRCC2 was significantly positively correlated with pathological T stage, N stage, and TNM stage." (PMID 39206620, 2024). "Therefore, we could predict the expression status of RAD51D and XRCC2 during homologous recombination to reflect the sensitivity of gastric cancer patients to platinum chemotherapy drugs." (PMID 39206620, 2024).
Infertility (3 papers, 2022 to 2024). "used whole-exome sequencing to sequence two patients with infertility and found that male patients with NOA had C. 41T>C (p.Leu14Pro) XRCC2 mutation, and believed that the occurrence of NOA in the family was caused by XRCC2 mutation." (PMID 38846492, 2024).
lung adenocarcinoma (3 papers, 2018 to 2024). A carcinoma that arises from the lung and is characterized by the presence of malignant glandular epithelial cells. "The ceRNA mechanism, involving genes like TENM4, XRCC2, HDAC5, CDKN1A, ARFGEF3, SNAP25-AS1, RP11-58O9.2, LINC01164, VLDLR-AS1, and RP11-14I17.2, may play a role in lung adenocarcinoma (LUAD) development linked to tumor hypoxia." (PMID 39236027, 2024). "In addition, previous study indicated that the XRCC2 gene showed more than five-fold higher expression in the patients with lung adenocarcinomas, compared to the control group." (PMID 39236027, 2024).
lymph node metastasis (3 papers, 2015 to 2024). "The expression levels of RAD51D and XRCC2 were significantly correlated with pathological T stage, N stage, number of lymph node metastases, lymph node metastasis rate, TNM stage, and Lauren's classification (p < 0.05)." (PMID 39206620, 2024). "An association was confirmed between XRCC2 Arg188His and XRCC3 Thr241Met polymorphisms and TNBC progression, assessed by the degree of lymph node metastases and histological grades." (PMID 24728564, 2015). "The XRCC2 radiomics score was significantly positively correlated with the N stage, number of lymph node metastases, lymph node metastasis rate, and TNM stage (p < 0.05) but was not significantly correlated with the T stage or Lauren's classification." (PMID 39206620, 2024).
triple-negative breast carcinoma (3 papers, 2015). An invasive breast carcinoma which is negative for expression of estrogen receptor (ER), progesterone receptor (PR), and human epidermal growth factor receptor 2 (HER2). "In the present work, a relationship was identified between XRCC2 Arg188His polymorphism and the incidence of triple-negative breast cancer." (PMID 24728564, 2015). "In the presented study, XRCC2 Arg188His genotype was associated with an elevated risk of triple-negative breast cancer in the Polish population." (PMID 24728564, 2015). "A correlation was found between the prevalence of the XRCC2 gene rs3218536 polymorphism and morbidity of triple-negative breast cancer in the female population in Poland." (PMID 26339569, 2015). "The obtained data show that Arg188His and Thr241Met polymorphisms of XRCC2/3 genes may be associated with the risk of triple-negative breast carcinoma occurrence." (PMID 24728564, 2015). "In the present study, the association between the Arg188His polymorphism of XRCC2 gene and Thr241Met polymorphism of XRCC3 gene and triple-negative breast cancer in the population of Polish women was investigated." (PMID 24728564, 2015). "Some correlation was observed between the XRCC2-Arg188His and XRCC3-Thr241Met polymorphisms and triple-negative breast cancer invasiveness." (PMID 24728564, 2015). "The aim of the present work was to evaluate associations between the risk of triple-negative breast cancer (TNBC) and polymorphisms in the genes, encoding for two key proteins of HRR: XRCC2 Arg188His (c." (PMID 24728564, 2015). "Two single nucleotide polymorphisms of XRCC2-41657C/T, and RAD51-172G/T were investigated in the reported study, as well as their association with human triple- negative breast cancer." (PMID 25743260, 2015). "In conclusion, XRCC2 Arg188His and XRCC3 Thr241Met polymorphisms may be regarded as predictive factors of triple-negative breast cancer in female population." (PMID 24728564, 2015). "In conclusion, the obtained data confirm the important role of RAD51 172G/T - but not of -41657C/T of XRCC2 gene polymorphism in triple-negative breast cancer aetiology." (PMID 25743260, 2015). "The obtained data suggest that the reported study may be the first observation of the polymorphisms in XRCC2 and XRCC3 genes, involved in the DNA repair pathway, to be associated with triple-negative breast carcinoma risk in the population of Polish women." (PMID 24728564, 2015). "The obtained results indicate that the polymorphism of RAD51, but not of XRCC2 gene, may be positively associated with the incidence of triple-negative breast carcinoma in the population of Polish women." (PMID 25743260, 2015). "The polymorphisms of the XRCC2 gene -41657C/T (rs718282) and of the RAD51 gene, −172G/T (rs1801321), were investigated by PCR-RFLP in 70 patients with triple-negative breast cancer and 70 age- and sex matched non-cancer controls." (PMID 25743260, 2015).
breast tumors (2 papers, 2015 to 2019). "Unfortunately, it is difficult to find reports in the available literature, which would directly bind RAD51 and XRCC2 SNP in DNA repair gene by HR with clinical-pathological features of breast tumour." (PMID 25743260, 2015). "Indeed, the size distribution of deletions and the presence of a few other types of non-clustered rearrangements in RAD51C−/−, XRCC2−/−, XRCC3−/−, BRCA2−/−, or PALB2−/− mutant cells closely resembled the predominant rearrangement signature of BRCA2-deficient breast tumors." (PMID 31727117, 2019).
head and neck cancer (2 papers, 2017 to 2021). A primary or metastatic malignant neoplasm affecting the head and neck. "A variety of cancers have been associated with XRCC2, such as breast, lung, pancreatic, and head and neck cancers." (PMID 34486486, 2021). "In this study, we successfully genotyped a total of five SNPs in different regions of XRCC2 gene such as promoter region, exonic region and intronic region and examined their possible association with head and neck cancer risk." (PMID 29038438, 2017). "We aimed to investigate the effect of hotspot variations of XRCC2 gene on the risk of head and neck cancer (HNC) in 400 patients and 400 controls." (PMID 29038438, 2017). "A significant association was observed between XRCC2 and head and neck cancer." (PMID 29038438, 2017). "Thus, an attempt was undertaken in this study to determine whether single nucleotide polymorphisms (SNPs) in XRCC2 gene are associated with head and neck cancer." (PMID 29038438, 2017). "Since XRCC2 genomic sequence is highly polymorphic, it is of interest to identify genetic defects which have a functional potential to affect the final repairing efficiency of XRCC2, and subsequently the development of head and neck cancer." (PMID 29038438, 2017).
hereditary cancer (2 papers, 2020 to 2023). Malignant neoplasms occurring in families at a rate greater than that expected by chance and caused by germline mutations in a specific gene. "A prospective cohort of 1021 unrelated cancer cases with clinical suspicion of hereditary cancer was screened for mutations in the following 14 FA genes: FANCA, FANCB, FANCC, FANCD2, FANCE, FANCF, FANCG/XRCC9, FANCI, FANCL/PHF9, FANCM, FANCP/SLX4, FANCQ/ERCC4, FANCR/RAD51 and FANCU/XRCC2." (PMID 32235514, 2020).
melanoma (2 papers, 2020 to 2021). A malignant, usually aggressive tumor composed of atypical, neoplastic melanocytes. "We have confirmed the regulation of four exemplary genes, namely RAD51, BRCA1, BRCA2, and XRCC2 by vemurafenib treatment in further BRAF-mutated melanoma cell lines using RT-qPCR analysis at the mRNA level and the regulation of Rad51 at protein level using immunoblot analysis." (PMID 32719412, 2020). "We found that several HRR-associated genes, including DDB2, RAD51, BRCA1, XRCC2 and BRCA2, are overexpressed in melanoma cells compared to primary melanocyte cultures, while the expression of the NER-associated genes XPA, ERCC1 and ERCC4 showed no clear differences." (PMID 32719412, 2020). "We have shown an overexpression of RAD51 and other HRR genes, DDB2, XRCC2, BRCA1 and BRCA2, in melanoma cell lines and this has a protective role against DNA damage accumulation after genotoxic stress." (PMID 32719412, 2020).
serous ovarian carcinoma (2 papers, 2015 to 2021). "Increased XRCC2 mRNA was linked to prolonged PFS for serous ovarian carcinoma women, HR=0.83 (0.71-0.97), P=0.021, but was not linked to OS for serous or endometrioid ovarian carcinoma patients." (PMID 34539898, 2021).
xeroderma pigmentosum group D (2 papers, 2011 to 2023). Any xeroderma pigmentosum in which the cause of the disease is a mutation in the ERCC2 gene. "A number of genetic variants have been reported to be associated with radiotherapy response for cancer, including XRCC1, X-ray repair cross complementing 2 (XRCC2), xeroderma pigmentosum group D (XPD), and EGFR." (PMID 36624463, 2023).
angiosarcoma (1 paper, 2023). A malignant tumor arising from the endothelial cells of the blood vessels. "EME1, FANCA, RAD51, TP53BP1, RAD51C, RPA1, and XRCC2 exhibited alterations in more than half the cases of the angiosarcoma cohort." (PMID 36779660, 2023).
Breast-ovarian cancer (1 paper, 2023). "In RAD51D we found the mutation R266C (Breast-ovarian cancer, familial), which interacts across the interface with XRCC2 and paralogous genes involved in the repair of DNA double-strand breaks by homologous recombination." (PMID 36690744, 2023). "Interestingly, we also found mutations at R239, to Trp/Gln/Gly, associated with Breast-ovarian cancer which interacts with Tyr119 in XRCC2, which itself is also annotated as having mutations linked to hereditary cancer-predisposing syndrome." (PMID 36690744, 2023).
choriocarcinoma (1 paper, 2019). An aggressive malignant tumor arising from trophoblastic cells. "In the second case the XRCC2 variant was detected in the seminoma portion of the primary tumor but absent from the choriocarcinoma." (PMID 30870501, 2019).
colorectal adenoma (1 paper, 2020). An adenoma that arises from the colon or rectum. "Previously, studies related to RAD51 and XRCC2 genes polymorphisms have recognized association between the distribution of these polymorphisms and the vulnerability of colorectal adenoma or cancer." (PMID 32458654, 2020).
diabetes (1 paper, 2025). "Additionally, we observed that CCNB2, XRCC2, and CENPI were elevated in BC tissues provided by patients with a diabetes history and associated with KI67 expression." (PMID 40202151, 2025).
endometrioid ovarian carcinomas (1 paper, 2021). "Higher mRNA level of XRCC2 was also not linked to PFS for endometrioid ovarian carcinoma patients." (PMID 34539898, 2021).
Erythema (1 paper, 2025). Redness of the skin, caused by hyperemia of the capillaries in the lower layers of the skin. "Polymorphisms in DNA repair genes (e.g., XRCC2, ERCC2, and ERCC1) and inflammatory mediators like IFNG were most linked to acute adverse effects, including erythema, desquamation, and oedema." (PMID 40507362, 2025).
esophageal squamous cell carcinoma (1 paper, 2015). Esophageal squamous cell carcinoma (ESCC) is a type of esophageal carcinoma (EC) that can affect any part of the esophagus, but is usually located in the upper or middle third. "Some reports documented that the XRCC2 -41657C/T genotype was related to increased esophageal squamous cell carcinoma (ESCC), gastric cardia adenocarcinoma (GCA) and in smoking- drinking-related laryngeal cancer risk." (PMID 25743260, 2015).
familial breast cancer (1 paper, 2013). "A significant association between rare XRCC2 variants and familial breast cancer was reported." (PMID 23383274, 2013).
female infertility (1 paper, 2024). Diminished or absent ability of a female to achieve conception. "While constitutional lack of Xrcc2 leads to almost complete fetal or perinatal lethality, mice carrying a deleterious variant in Xxrc2 present male infertility due to NOA and female infertility or severe female subfertility due to atrophic ovaries deprived of follicles." (PMID 38764035, 2024).
Hereditary breast cancer (1 paper, 2019). "We identified a single XRCC2 protein-truncating mutation (c.96delT, p.Phe32fs) in 3 of 617 women with hereditary breast cancer." (PMID 31463769, 2019).
Hyperglycemia (1 paper, 2025). An increased concentration of glucose in the blood. "Hyperglycemia treatment elevated the expression levels of CCNB2, XRCC2, and CENPI in BC cells, which correlated with increased cell proliferation and mobility." (PMID 40202151, 2025).
hyperlipidaemia (1 paper, 2019). "In addition, EHM inhibited hyperlipidaemia by restoring the expression of genes and proteins related to DNA repair and energy metabolism, and proteins such as Hdac2, Xrcc2, Xrcc3, Uhrf1, and Prkar2b were identified as molecular targets playing key roles in ameliorating hyperlipidaemia." (PMID 31545933, 2019).
metastatic colorectal cancer (1 paper, 2021). "In addition, studies have shown that KIF14, a co-expressed gene positively associated with XRCC2, plays an oncogenic role in numerous cancers, FBXW4, a gene negatively associated with XRCC2, acts as a protective factor in metastatic colorectal cancer." (PMID 34051735, 2021).